TFRC (transferrin receptor)
Diseases named in the same sentence as TFRC in open-access papers (continued):
Sharing a sentence is not in itself a finding about the gene and the disease.
Hyperinsulinemia (2 papers, 2021 to 2023). An increased concentration of insulin in the blood. "Hyperinsulinemia, however, did not change GUSB, slightly decreased CTSL expression and increased TFRC levels, all of these changes being significantly different from the metformin effects." (PMID 33690729, 2021).
hyperuricemia (2 papers, 2024). An abnormally high level of uric acid. "A nationwide population study conducted in China demonstrated that levels of serum ferritin (SF), transferrin, and soluble transferrin receptor (sTfR) are positively associated with the risk of hyperuricemia." (PMID 39022306, 2024). "All patients for whom the measurement was available showed increased serum transferrin receptor-1 while no patient showed hyperuricemia or an increased serum creatinine." (PMID 39335726, 2024).
insulin-dependent diabetes (2 papers, 2018 to 2025). "In pregnant women with insulin-dependent diabetes, increased N-glycosylation of transferrin receptor (TfR) released from the placenta can reduce its binding capacity to transferrin (Tf), thereby reducing iron transport in the placenta." (PMID 40977974, 2025). "Cord plasma biomarkers of high iron status were non-significantly associated with higher risk of type 1 diabetes (ferritin OR = 1.05 [95%CI: 0.99–1.13] per 50 mg/L increase; soluble transferrin receptor: OR = 0.91 [95%CI: 0.81–1.01] per 0.5 mg/L increase)." (PMID 29899542, 2018).
intracerebral hemorrhage (2 papers, 2022 to 2024). A cerebrovascular disorder characterized by bleeding into one or both cerebral hemispheres including the basal ganglia and the cerebral cortex. "Furthermore, a study on intracerebral hemorrhage indicated that METTL3 induced the development of ferroptosis by regulating the m6A level of TFRC mRNA." (PMID 38221933, 2024).
iron (2 papers, 2021 to 2024). "The H63D mutation alters the normal HFE product’s affinity for its ligand, the transferrin receptor, contributing to an iron overload state." (PMID 39036618, 2024).
laryngeal carcinoma (2 papers, 2023 to 2024). Carcinoma that arises from the laryngeal epithelium. "LINC00888 competes with the gene transferrin receptor (TFRC) for the chance of interacting with miR-378 g and leads to the upregulation of TFRC, thereby accelerating laryngeal cancer cell growth and mobility." (PMID 38807101, 2024).
meningitis (2 papers, 2024 to 2025). A disorder characterized by acute inflammation of the meninges of the brain and/or spinal cord. "Transferrin receptor (TfR) transcytosis is an essential strategy for delivering therapeutics into the brain and is exploited by meningitis-causing bacteria to penetrate the blood–brain barrier (BBB)." (PMID 40601634, 2025). "Transferrin receptor (TfR) transcytosis, one of the few active transcytosis pathways in HBMECs, is extensively utilized for drug transport across the BBB and employed by meningitis-causing bacteria to penetrate into the brain." (PMID 40601634, 2025). "Additionally, EVs can also fuse with Streptococcus pneumoniae, group B Streptococcus, and neonatal meningitis Escherichia coli to hitchhike on transferrin receptor (TfR) transcytosis to cross the BBB and be linked to meningitis." (PMID 39597520, 2024).
mesothelioma (2 papers, 2022 to 2023). A usually malignant and aggressive neoplasm of the mesothelium which is often associated with exposure to asbestos. "Studies have shown that YAP pathway activation in mesothelioma tissue enhances iron death sensitivity through ACSL4 and TFRC, and YAP, ACSL4, and TFRC are expected to be biological markers for clinical prediction of iron death sensitivity in mesothelioma." (PMID 35906548, 2022).
parasite (2 papers, 2006 to 2022). "During malaria infection, TFRC knockdown decreased parasite-localized lipid peroxides, and led to a substantial decrease in the efficacy of erastin in liver-stage parasite infection." (PMID 35821227, 2022).
spinal muscular atrophy (2 papers, 2022 to 2023). A motor neuron disease that affect the muscles, and characterized by muscle weakness and atrophy resulting from progressive degeneration and irreversible loss of the anterior horn cells in the spinal cord (i.e., lower motor neurons) and the brain stem nuclei. "Conjugating an anti-transferrin receptor Ab (anti-TfR Ab) to PMO enables an increase in SMN2 mRNA level in the CNS when injected systematically to a spinal muscular atrophy mouse model." (PMID 37759475, 2023). "We investigated conjugation of ASOs to an antibody against the murine transferrin receptor, 8D3130, and evaluated it via systemic administration in mouse models of the neurodegenerative disease spinal muscular atrophy (SMA)." (PMID 36346674, 2022).
synovitis (2 papers, 2022 to 2024). Inflammation of a synovial membrane. "In a lipopolysaccharide-induced synovitis model in one report, an increase in iron content and TFRC, as well as a decrease in GPX4, SLC7A11 and SLC3A2, was described, leading to increased cell death." (PMID 39513899, 2024).
vitiligo (2 papers, 2022). Generalized well circumscribed patches of leukoderma that are generally distributed over symmetric body locations and is due to autoimmune destruction of melanocytes. "In contrast, transferrin receptor protein 1 (TfR) was observed to be overexpressed in both lesional and non-lesional areas of vitiligo." (PMID 36439174, 2022).
Airway obstruction (1 paper, 2014). Obstruction of conducting airways of the lung. "In BAL cells, the mRNA expression of transferrin, transferrin receptor and ferritin correlated with airway obstruction." (PMID 24789352, 2014).
aortic valve stenosis (1 paper, 2021). Aortic valve stenosis (AVS) is a condition characterized by narrowing of the heart's aortic valve opening. "Associations were found between the development of aortic valve stenosis in patients with coronary atherosclerosis and certain proteins, such as differential growth factor-15, galectin-4, the Willebrand factor, interleukin 17, transferrin receptor protein 1 and PCSK9." (PMID 34948066, 2021).
asplenia (1 paper, 2022). "We found that the percent of immature RBCs CD71+, reticulocytes expressing the transferrin receptor on the cell surface was lower in the hypersplenism vs. asplenia/hyposplenism group." (PMID 36105295, 2022). "We found that the percent of immature RBCs CD71+, reticulocytes expressing the transferrin receptor on the cell surface was lower in the hypersplenism vs. asplenia/hyposplenism group (mean % 1.5 ± 0.4 vs. 4.2 ± 2.1; respectively, p = 0.013)." (PMID 36105295, 2022).
bacterial vaginosis (1 paper, 2020). Infection caused by bacterial overgrowth in the vagina. "It is currently unclear if this process is related to proliferation of siderophore producing microorganisms within the vaginal tract or some other mechanism, as increases in soluble transferrin receptor (sTfR) was noted in patients with bacterial vaginosis during pregnancy (BV)." (PMID 33302392, 2020).
bone cancer (1 paper, 2023). A primary or metastatic malignant neoplasm affecting the bone or articular cartilage. "Moreover, analysis of a Cancer Cell Line Encyclopedia (CCLE) dataset revealed that TFRC protein expression was high in soft tissue sarcoma cell lines but relatively low in bone cancer cell lines." (PMID 37444594, 2023).
bone marrow failure (1 paper, 2021). "In addition, the soluble form of transferrin receptor (sTfR), a possible indicator of bone marrow failure when receiving chemotherapy, was confirmed to be suppressed during chemotherapy, indicating that sTfR may be a potential indicator of required transfusion." (PMID 33435254, 2021).
brain inflammation (1 paper, 2026). "Moreover, brain inflammation decreased iron in BMV as evidenced by an increase in the transferrin receptor and decreased FTH1, suggestive of increased iron uptake." (PMID 41871808, 2026).
cerebral malaria (1 paper, 2024). A sequestration of Plasmodium falciparum in the brain, which can cause coma and/or seizures. "In the proteome of parasitized red blood cells, we also observed an increased transferrin receptor abundance, suggesting a more significant invasion of reticulocytes or erythroblasts in patients experiencing cerebral malaria." (PMID 38297098, 2024).
cervical (1 paper, 2025). "Notably, the mechanistic basis of TFRC in cervical carcinogenesis and malignant progression remains unelucidated." (PMID 40303995, 2025).
cholestasis (1 paper, 2024). Impairment of the bile flow caused by obstruction within the liver, or outside the liver in the bile duct system. "Strikingly, Ac2-26 therapy inhibits transferrin receptor 1 over-expression, iron accumulation, cytokine IL-17 release and the production of its receptor IL-17R, as well as astrocyte activation in the dorsal horn of spinal cord in mouse with dermatitis and cholestasis." (PMID 38790419, 2024).
chronic heart failure (1 paper, 2018). "We did not measure other markers of ID, such as the soluble transferrin receptor, hepcidin or the ferritin index that may better evaluate iron metabolism in patients with chronic heart failure." (PMID 30382817, 2018).
diphtheria (1 paper, 2020). A Gram-positive bacterial infection caused by Corynebacterium diphtheriae. "Associations between serum transferrin receptor and anti-diphtheria, anti-pneumococcus serotype 19 and anti-polio serotype 2 serum IgG concentrations and/or seroconversion, in the birth cohort of Kenyan infants." (PMID 32754150, 2020).
dysplasia (1 paper, 2014). A usually neoplastic transformation of the cell, associated with altered architectural tissue patterns. "Given the combined findings of the TFRC expression and cell growth studies, TFRC is a potential cell surface marker for dysplasia and OSCC, and OSCC cell growth appears to be partly dependent on the TFRC expression rate." (PMID 24890018, 2014). "The expression rate of TFRC in OSCC was significantly higher than that in dysplasia, suggesting that OSCC disease progression might be related to TFRC expression." (PMID 24890018, 2014). "Therefore, in future experiments, we should carefully determine the relationship between the TFRC expression time course and disease progression in cases of OSCC that have developed from dysplasia as well as the effectiveness of the anti-TFRC antibody against OSCC." (PMID 24890018, 2014).
endotoxemia (1 paper, 2011). "We next examined whether markers for iron handling, the transferrin receptor (TFR-1) and astrocyte (GFAP) and microglial (IBA-1) activation were altered by LPS-induced endotoxemia." (PMID 21943033, 2011).
enteritis (1 paper, 2024). Inflammation of the small intestine. "In addition, a previous study found that miR-320a inhibited the infection and replication of enteritis virus in F81 cells by targeting the 3’UTR of transferrin receptor." (PMID 38750508, 2024).
epilepsy (1 paper, 2021). A brain disorder characterized by episodes of abnormally increased neuronal discharge resulting in transient episodes of sensory or motor neurological dysfunction, or psychic dysfunction. "Interestingly, strong TFRC expression in punctate, astrocytic end-feet around the microvasculature could be detected, which might indicate a shift in control over iron shuttling from endothelium to astrocytes in epilepsy." (PMID 34292399, 2021).
esophageal tumors (1 paper, 2022). "There is a noted increase in the levels of transferrin receptor 1 (TFR1) in clinical isolates of esophageal tumors." (PMID 36698390, 2022).
experimental autoimmune encephalomyelitis (1 paper, 2023). An autoimmune demyelinating disease of the central nervous system that is produced experimentally in animals by the injection of homogenized brain or spinal cord in Freund's adjuvant. "In a study where MS-specific membrane-associated biomarkers were investigated in experimental autoimmune encephalomyelitis (EAE), an animal model of MS, it was shown that TFRC protein expression was down-regulated in PBMCs." (PMID 37018152, 2023).
Fever (1 paper, 2024). Body temperature elevated above the normal range. "While best known for the cellular uptake of iron through endocytosis, TFRC is a receptor for new-world hemorrhagic fever arenaviruses, and can endocytose IgA." (PMID 38625739, 2024).
Gaucher disease (1 paper, 2019). Gaucher disease (GD) is a lysosomal storage disorder encompassing three main forms (types 1, 2 and 3), a fetal form and a variant with cardiac involvement (Gaucher disease - ophthalmoplegia - cardiovascular calcification or Gaucher-like disease). "In addition, a recent paper demonstrated that cells taken from patients with Gaucher disease displayed restricted lateral lipid mobility and exhibited reduced rates of transferrin receptor endocytosis." (PMID 30918081, 2019).
glutathione metabolism disorder (1 paper, 2025). "For example, the loss of TFRC in skeletal muscle SCs may contribute the absorption of non-transferrin-bound iron and cause Fe2+ accumulation, glutathione metabolism disorder, and lipid peroxidation, inducing skeletal muscle ferroptosis." (PMID 40938883, 2025).
HCMV infection (1 paper, 2025). "Studies have shown that during HCMV infection, the expression of transferrin receptor 1 (TFR1) increases, resulting in heightened iron levels that are critical for the initial stages of the infectio." (PMID 41170318, 2025).
Hydrocephalus (1 paper, 2020). Hydrocephalus is an active distension of the ventricular system of the brain resulting from inadequate passage of CSF from its point of production within the cerebral ventricles to its point of absorption into the systemic circulation. "Although some variation and severity were observed, knockdown of the corresponding six genes (BMPR2A, BMPR2B, TFRC, F11R, PTPRS, and PGRMC2) resulted predominantly in ciliopathic disorders, including abnormal development, hydrocephalus, kidney cysts, and left–right asymmetry in cardiac looping." (PMID 32832346, 2020).
inflammatory breast carcinoma (1 paper, 2014). An advanced, invasive breast adenocarcinoma characterized by the presence of distinct changes in the overlying skin. "A proteomics analysis showed that TFRC is highly expressed in inflammatory breast cancer." (PMID 25419056, 2014).
Inguinal hernia (1 paper, 2024). Protrusion of the contents of the abdominal cavity through the inguinal canal. "Besides, both TFRC and TNF could significantly increase the risk of inguinal hernia (TFRC: IVW: OR [95%]=1.0028 [1.0009 to 1.0046], p = 0.003; TNF: Wald ratio: OR [95%]=1.0009 [1.0 to 1.0019], p = 0.04)." (PMID 38591204, 2024).
malignant mesothelioma (1 paper, 2022). A malignant neoplasm of the pleura or peritoneum, arising from mesothelial cells. "Inhibition of CA9 could decrease the viability and migration of malignant mesothelioma cells, while Fe2+ is increased via upregulating transferrin receptor and downregulating ferritin." (PMID 36230613, 2022).
mammary adenocarcinomas (1 paper, 2022). "TFRC knockdown decreased intracellular total iron, suppressed tumor growth and metastasis in human and mouse mammary adenocarcinomas." (PMID 35752862, 2022).
mastitis (1 paper, 2022). Inflammation of breast tissue during lactation or postpartum due to an obstructed duct or infection. "Of the 12 co-expressed down-regulated genes, TFRC and MAPK6 are thought to be associated with immunity and mastitis, LARP1B and ODC1 are associated with reproductive traits, such as oestrogen and sperm quality." (PMID 35480317, 2022).
Micrognathia (1 paper, 2016). Developmental hypoplasia of the mandible. "Here we report that neural crest cell (NCC)-specific knockout of transferrin receptor (Tfrc), a well known transferrin transporter protein, caused micrognathia, cleft palate, severe respiratory distress and inability to suckle in mice, which highly resemble human PRS." (PMID 27362800, 2016).
migraine (1 paper, 2025). "Six proteins were significantly upregulated in migraine with a >1.5 fold change compared to controls and Padj < 0.05 (FAM3C, GOLM1, PSA7, ENPP2, DSG2, TFRC); 3 proteins were significantly downregulated (FGL1, CAH2, AMYP)." (PMID 40852402, 2025).
Myocardial fibrosis (1 paper, 2022). "Further, physical inactivity was associated with elevated plasma levels of Metalloproteinase inhibitor 4, Soluble interleukin 1 receptor-like 1, Elafin and Transferrin receptor protein 1, which are implicated in myocardial fibrosis, migration and apoptosis." (PMID 35265689, 2022).
nephrotoxicity (1 paper, 2025). Toxicity that causes injury to the kidney or damages its function. "The expression of TFRC, ACSL4, and STEAP3, all of which promote ferroptosis, was significantly upregulated in the APAP-induced nephrotoxicity group." (PMID 41249093, 2025).
normocytic anemia (1 paper, 2026). Anemia in which the red blood cell volume is normal. "We found that in patients with macrocytic and normocytic anemia, the level of erythropoietin (EPO) was positively correlated with soluble transferrin receptor (STFR)." (PMID 42136851, 2026).
Osteoblastoma (1 paper, 2025). A rare benign bone-forming neoplasm usually arising from the spine. "We unexpectedly detected the significant upregulation of TFRC in osteoclasts from osteoblastoma tissues." (PMID 40510157, 2025).
pheochromocytoma (1 paper, 2023). "TFRC levels were compared in abdominal mesenteric fat of pheochromocytoma patients versus control subjects, and overweight versus lean subjects." (PMID 37646182, 2023). "Of clinical relevance, we found that TFRC levels were significantly increased in adipose tissues from pheochromocytoma patients compared to control subjects." (PMID 37646182, 2023). "Of note, we found that, in abdominal mesenteric regions of fat, TFRC levels were increased in pheochromocytoma patients and decreased in overweight patients, compared to their control counterparts." (PMID 37646182, 2023). "In the present study, we reported that TFRC was strongly expressed in abdominal fat tissue from pheochromocytoma patients and decreased in overweight patients." (PMID 37646182, 2023). "TFRC levels is elevated in activated human thermogenic fat from pheochromocytoma patients and downregulated in fat from overweight patients compared to their control subjects, respectively." (PMID 37646182, 2023). "Thus, the increased TFRC levels in adipose tissues from pheochromocytoma patients are likely due to the high browning status." (PMID 37646182, 2023).
presbycusis (1 paper, 2020). Bilateral hearing loss caused by progressive degeneration of cochlear structures and central auditory pathways, typically associated with the aging process. "In an aging model of presbycusis, increased expression of transferrin receptor 1, iron accumulation, and malondialdehyde and a decreasing level of glutathione and superoxide dismutase were observed, suggesting an activation of ferroptotic activity." (PMID 33019767, 2020).
prion disease (1 paper, 2009). A transmissible disease that is caused by a protein that is able to induce abnormal folding of normal cellular proteins, leading to characteristic spongiform brain changes, which are associated with neuronal loss without an inflammatory response. "In this report, we demonstrate that prion disease–affected human, hamster, and mouse brains show increased total and redox-active Fe (II) iron, and a paradoxical increase in major iron uptake proteins transferrin (Tf) and transferrin receptor (TfR) at the end stage of disease." (PMID 19283067, 2009).
psychosis (1 paper, 2023). "This fact, together with the higher expression of the iron transporter TFRC, can understood as indicative of an enhanced iron accumulation and entry in the trophoblasts of women who are affected by a first episode of psychosis." (PMID 36671505, 2023). "Our results demonstrate an increased presence of iron deposits that are accompanied by a further expression of TFRC, ACSL-4, ALOX-5, MDA, and GPX4—all of which are observed in the placenta tissue of women who have suffered from a first episode of psychosis." (PMID 36671505, 2023).